PAK4 (p21 (RAC1) activated kinase 4)
Diseases named in the same sentence as PAK4 in open-access papers (continued):
Sharing a sentence is not in itself a finding about the gene and the disease.
tumor (continued). "Moreover, bioluminescence imaging also showed that PAK4 knockdown significantly suppressed tumor growth and improved chemosensitivity to cisplatin." (PMID 38238316, 2024). "Therefore, we analysed the expression of PD-L1 on tumour cells following PAK4 inhibition in OSCC tumour-bearing mice and determined the function of DCs within tumour tissues." (PMID 38890401, 2024). "PAK4 inhibitor-treated mice showed significantly delayed tumour growth compared with control mice." (PMID 38890401, 2024). "More importantly, our findings lay down a solid base for further testing the combined effects of PAK1 and PAK4 on the tumour immune response of PDA using selective PAK inhibitors, which will provide a clear guide for the clinical translation of this basic research work." (PMID 38797819, 2024). "Inactivation of PAK4 reprograms transcriptome in ECs and normalizes tumor vasculature." (PMID 38580870, 2024). "Additionally, it was found that the expression level of CD80 on CD11c+CD103+ DCs in the tumours of mice treated with PAK4 inhibitors was significantly higher." (PMID 38890401, 2024). "Interestingly, this study also indicates that miR-199a/b-3p, the 11th most downregulated miRNA in our results, is a potential therapeutic agent because it can target tumor-promoting PAK4 to suppress HCC growth by inhibiting the PAK4/Raf/MEK/ERK pathway." (PMID 38256049, 2024). "Furthermore, inhibition of PAK4 demonstrated the potential to sensitize resistant tumor cells through modulating endoplasmic reticulum stress." (PMID 38238316, 2024). "However, little is known about the expression of PAK4 and about the anti-tumour and immunomodulatory effects of PAK4 inhibition in OSCC." (PMID 38890401, 2024). "Recently studies have demonstrated the anti-tumour immune effect by targeting PAK4, which could be because of the activation of the Wnt/β-catenin pathway." (PMID 38890401, 2024). "On the basis of these results, PAK4 targeting could enhance the host anti-tumour immunity via T-cells by reducing PD-L1 on tumour cells and activating DCs, especially CD103 + DCs through suppression of the Wnt/β-catenin pathway in OSCC." (PMID 38890401, 2024). "Studies have shown that RAC1 can target PAK4‐mediated pyroptosis in tumor cells." (PMID 39224538, 2024). "In the univariate analysis, consistent with previous reports that PAK4 is an indicator of aggressive tumor behavior and potentially affects patient outcomes, PAK4 and HMGCS2 expression was significantly associated with relapse-free (RFS) and overall survival (OS)." (PMID 37591884, 2023). "PAK4 induced resistance to immune checkpoint inhibitors by changing the tumor microenvironment." (PMID 36980457, 2023). "Below, we will discuss the role of PAK 1 and PAK4 in tumour vasculature." (PMID 38067120, 2023). "Moreover, KD-fed Pak4 LKO mice exhibited reduced tumor formation compared to WT mice on the same diet." (PMID 37591884, 2023). "However, it has recently been shown that miR-199a/b-3p has also a tumor-inhibiting effect via interfering with the MAPK/ERK pathway by suppressing the p21-activated kinase 4 (PAK4)." (PMID 37108330, 2023). "Afterward, these cell activities and characteristics can lead to volume increase, diffusion, metastasis, and reduced sensitivity to chemotherapy and immunotherapy of tumor tissues, because of which the prognosis of tumor patients with high PAK4 expression is often poor." (PMID 35800076, 2022). "The combination resulted in a significantly slower tumor growth compared with compound A0317859 or anti-PD-1 alone, which parallels the results of PAK4 KO and KD tumors and provides a new rationale for the combination of PD-1 blockade with a specific PAK4 kinase inhibitor." (PMID 36588582, 2022). "PAK4, a target of tumor immune escape, is of high importance to regulating antitumor immunity." (PMID 35800076, 2022). "PAK4 is prominently involved in generating tumor drug resistance via multiple pathways." (PMID 35800076, 2022).
tumor (continued). "Altogether, we characterized the tumor transcriptome of B16 PAK4 KO cells both, in vitro and in vivo, and determined that the main differences between PAK4 KO and WT transcriptomes are found in genes and cell signatures associated with the extracellular matrix." (PMID 36588582, 2022). "In addition to regulating the internal activities of cell metastasis, PAK4 promotes tumor cell migration and invasion via multiple pathways." (PMID 35800076, 2022). "PAK4 is also crucial in biological processes, including the occurrence, proliferation, survival, migration, invasion, drug resistance, and immune escape of tumor cells." (PMID 35800076, 2022). "KPT–9274 stands out in targeting PAK4 to improve the efficacy of tumor therapy." (PMID 35800076, 2022). "Through siRNA verification experiment and bioinformatics analysis, PAK4 was screened out as a related kinase that could enhance the anti-tumor effect of ORFV." (PMID 35401439, 2022). "PAK4 undergoes gene amplification in a variety of tumor cells." (PMID 35800076, 2022). "From preneoplastic cells losing homeostasis to tumor cells with continuous proliferation and from migration and invasion to treatment-resistant tumor cells, complex biological processes and rich signaling involve PAK4." (PMID 35800076, 2022). "In summary, in this study we showed how PAK4 inhibition remodels the tumor microenvironment, enabling the infiltration of key immune cell subtypes and changing the expression of genes involved in the tumor architecture." (PMID 36588582, 2022). "Also, PAK4 is closely related to tumor infiltration depth, lymph node metastasis, stage classification, and other pathological indicators, whose clinical application prospects are broad." (PMID 35800076, 2022). "Furthermore, PAK4 was also found as an important regulator of tumor immunity, thus opening a novel landscape for PAK4-related therapy." (PMID 36105226, 2022). "Activation of PAK4 improves tumor resistance to PD–1 blockade." (PMID 35800076, 2022). "Furthermore, tumors with genetic PAK4 deletion are more sensitive to PD–1 blockade, and the tumor can completely subside under the action of anti-PD–1 drugs." (PMID 35800076, 2022). "Additionally, it was shown that anti-tumor immune cell infiltration was increased following PAK4 knockdown, whereas wild type tumors remained devoid of immune cell infiltration." (PMID 36594908, 2021). "Moreover, both in vitro and in vivo, the PAK4/Raf/MEK/ERK pathway is inhibited by miRNA-199a targeting tumor-promoting PAK4 to suppress HCC growth." (PMID 34582645, 2021). "PCACP significantly inhibited HCC cell proliferation and tumor growth by targeting mTOR (mechanistic target of rapamycin), PAK4 (p21-Activated kinase 4), RHOC (Rho-related GTP-binding protein) and epithelial mesenchymal transition (EMT) pathways both in vitro and in vivo." (PMID 34072348, 2021). "Recently, numerous studies have indicated that PAK4 involving in tumor metastasis." (PMID 32549768, 2020). "Sequencing identified germline and tumor amplified, expressed, high-impact druggable variants in two genes (ABL1, NOTCH1) and expressed, medium impact variants in three additional genes (MDM4, PAK4, MAP4K5)." (PMID 31208434, 2019). "More importantly, PAK4-NAMPT RNAi inhibited the growth of BON-1 tumor in vivo." (PMID 31795447, 2019). "miR-199a/b-3p has been found to target the HCC tumor-promoting PAK4 by repression of PAK4/Raf/MEK/ERK pathway both in vitro and in vivo, suggesting that miR-199a/b-3p could be a potential therapeutic option for HCC." (PMID 31056726, 2019). "Also this impaired PyMT-driven tumor initiation is consistent with a role for PAK4 in senescence evasion, an early event in tumorigenesis." (PMID 31399573, 2019). "Interestingly, we observed a selectivity against Cre-positive cells in tumors that arose in PyMT;PAK4MEp−/− mice, which likely underscores the here observed role of PAK4 in tumor development." (PMID 31399573, 2019).
tumor (continued). "Depletion of CD8 T-cells abrogated the anti-tumor efficacy observed in the B16 PAK4 KO group." (PMID 30400822, 2018). "Importantly, Pak4 suppression inhibits E2 induced EC tumor growth in vivo, in a mouse xenograft model." (PMID 28978098, 2017). "Moreover, both PI3K and AKT inhibitors (LY294002 and MK2206) blocked the PAK4-induced tumor cell migration and invasion." (PMID 28407679, 2017). "PAK4 overexpression also promoted tumor cell migration in a wound healing assay." (PMID 28407679, 2017). "Both cytoplasmic and nuclear staining of PAK4 was seen in tumor cells." (PMID 28407679, 2017). "Additionally, wound healing assays showed PAK4 siRNA #2 or #3 significantly inhibited tumor cell migration (p < 0.01)." (PMID 28407679, 2017). "Moreover, both in vitro and in vivo, the PAK4/Raf/MEK/ERK pathway is inhibited by miR-199a/b-3p targeting tumor-promoting PAK4 to suppress HCC growth." (PMID 27275325, 2016). "Furthermore, both in vitro and in vivo, the PAK4/Raf/MEK/ERK pathway is inhibited by miR-199a/b-3p targeting tumour-promoting PAK4 to suppress HCC growth." (PMID 24853455, 2014). "Similarly, Pak4 knockdown suppresses MDA-MB-231 breast xenograft tumor formation in nude mice in vivo." (PMID 23732710, 2013). "In addition, miR-145 also inhibited p-ERK expression by targeting PAK4, leading to inhibition of tumor growth." (PMID 24312276, 2013). "In mice, Pak4 overexpression leads to tumor formation in xenograft studies." (PMID 23326684, 2012). "Another study in HCC showed that the decrement of miR-199a-3p significantly correlated with poor survival of patients, and it could target tumor-promoting PAK4 to suppress HCC growth through inhibiting the PAK4/RAF/MEK/ERK pathway both in vitro and in vivo." (PMID 22942713, 2012). "However, the association of PAK4-staining intensity was not significantly different from that of other characteristics, including age and sex of patients, location of tumours, differentiation, category N, stage in the TNM classification, smoking, or drinking." (PMID 38890401, 2024). "In addition, CD103+ DCs, a subset of DCs, may play an important role in promoting the anti-tumour immune responses via PAK4 inhibition." (PMID 38890401, 2024). "Inhibiting PAK4 might contribute to better response towards anti-tumor treatment." (PMID 38807162, 2024). "Furthermore, a cell adhesion signature with genes that play a role in the ECM and hence, could directly impact the tumor organization showed that the increase was specific for the PAK4 KO treated tumors." (PMID 36588582, 2022). "In addition, the direct interaction of Pak4 with Inka2-iBox is attributable to the anti-tumor effect of Inka2; however, the physiological function of Inka2 in neurons remains unclear." (PMID 36301793, 2022). "In addition, PAK4 is involved in the regulation of the anti-tumor immune response and is usually associated with a lack of response to PD-1 blockade." (PMID 35328227, 2022). "However, only an increased level of phosphor-PAK4, but not the expression of PAK4, was observed upon JEV-infection, suggesting that the upstream signaling regulating PAK4 activation in JEV-infected astrocytes may be different from other tumor cells." (PMID 28680855, 2017). "Our recent study showed an upregulation of cytotoxic CD8+ T-cell infiltration by PAK4 KO PDA cells, which led to tumor regression in murine syngeneic PDA models." (PMID 39941877, 2025). "Decreased vascular density was accompanied by increased tumour hypoxia, indicating impaired perfusion following PAK1 or PAK4 knockout." (PMID 40943273, 2025). "Our data provides a comprehensive comparison of DepMap dependency scores for PAK1, PAK2, PAK3, PAK4, PAK5, and PAK6, based on CRISPR analysis of 1100 tumor cell lines and RNAi analysis of 711 cell lines." (PMID 39756822, 2025).
tumor (continued). "While the immunomodulatory roles of PAK1 and PAK4 in PDA have been investigated, the impact of PAK on tumour vasculature and how these vascular changes influence the immune system, including T-cells and dendritic cells, remains poorly understood." (PMID 40943273, 2025). "PAK1 inhibition promotes vascular normalisation and an immune-permissive tumour microenvironment (TME), whereas PAK4 inhibition enhances gemcitabine response by increasing vessel calibre and downregulating DNA repair pathways." (PMID 41228228, 2025). "By impeding downstream molecular signaling mediated by PAK4, CZH226 effectively suppresses tumor cell migration and invasion." (PMID 40332759, 2025). "Manipulating PAK4 expression was shown to modulate WNT/β-catenin signaling, augmenting the presence of tumor-infiltrating T cells and improving responsiveness to PD-1 blockade therapy." (PMID 40332759, 2025). "p21-activated kinase 4 (PAK4), a member of the PAK family (PAK1-6), was initially recognized for its role in tumor development." (PMID 41023133, 2025). "In RCC, PROTAC PpD promotes the ubiquitinated degradation of P21-activated kinase-4 (PAK4), which in turn inhibits tumor proliferation and increases tumor cell death by immune cells." (PMID 40225869, 2025). "Here, we examined the therapeutic efficacy of inhibiting p21 activated kinase 4 (PAK4) in OSCC and determined its immunomodulatory effect by focusing on the enhancement of anti-tumour effects." (PMID 38890401, 2024). "Overall, these data provide strong evidence supporting the contribution of PAK4 signalling to the growth and survival of OSCC cells and to the anti-tumour efficacy of PAK4 inhibitor via modulation of these cellular processes." (PMID 38890401, 2024). "As such, inhibition of PAK4 reduces expression of Slug and Zeb-1, upregulating expression of VCAM-1 and Claudin-14 in tumor ECs, which eventually enhances T cell adhesion and improves CAR T cell immunotherapy." (PMID 38580870, 2024). "By one week, PAK double KO further suppressed the tumour growth compared to single PAK KO, indicating a synergistic effect of PAK1 and PAK4." (PMID 38797819, 2024). "Together PAK1 and PAK4 double KO stimulated a sustained increase of infiltration of active CD8 + T cells, leading to a complete tumour regression." (PMID 38797819, 2024). "We also investigated the effects of in vivo administration of a PAK4 inhibitor on immune cell distribution and T-cell immune responses in OSCC tumour-bearing mice." (PMID 38890401, 2024). "Given the findings that PAK4 KO tumour regressed one week after cell injection, we further examined PAK WT vs KO tumour growth within the first week." (PMID 38797819, 2024). "In the present study, we examined the effects of PAK4 inhibition as a therapeutic target in OSCC and investigated its immunomodulatory effects by focusing on the enhancement of anti-tumour effects." (PMID 38890401, 2024). "Our recent work shows that tumor ECs undergo a mesenchymal transformation, i.e., Endo-MT, to induce Snail/Slug-dependent aberrant vascularization via HGF/c-Met–, PDGF/PDGFR-β–, and PAK4-mediated mechanisms." (PMID 38416830, 2024). "For example, in ESCC, several SE-related oncogenes influence tumor proliferation, such as RUNX1, DNAJB1, and PAK4." (PMID 37501079, 2023). "Immunohistochemical expression of PAK4 and PHF8 was observed in both the nuclei and cytoplasm of tumor cells in human GBC tissue." (PMID 36980457, 2023). "In GBCs, the expression of PAK4 and PHF8 was observed in both the nuclei and cytoplasm of tumor cells." (PMID 36980457, 2023). "The combination of the PAK4 inhibitor, KPT-9274, and NAMPT modulators (KPT-9307) more effectively suppressed tumour growth in a xenografted mouse model." (PMID 38067120, 2023). "Blood and hepatic levels of βOHB were higher in Pak4 LKO than WT mice, and tumor weights were inversely correlated with βOHB levels." (PMID 37591884, 2023).
tumor (continued). "In a subcutaneous tumor model, Hepa1-6 cells were subcutaneously implanted into WT and Pak4 LKO mice, and tumor size was monitored while the animals were fed a NCD or KD." (PMID 37591884, 2023). "Overexpression of PAK4 can activate tumor signaling pathways, such as the PI3K/AKT and RAF/MEK/ERK pathways, while low expression of PAK4 can inhibit the growth of ESCC cells." (PMID 37501079, 2023). "Specifically, we found that in the tumor tissues of HCC patients, PAK4 protein expression inversely correlated with ketone body levels." (PMID 37591884, 2023). "In a mouse tumor model, the use of KPT-9274, a specific inhibitor of PAK4, or knocking down PAK4 expression, resulted in an increase in cytotoxic T-lymphocyte infiltration within tumors, leading to improved therapeutic outcomes of PD-1 blockade." (PMID 37511431, 2023). "They identified p21-activated kinase 4 (PAK-4) as a regulator of aberrant vascularization in GBM and used pharmacological inhibitor of PAK-4 to normalize tumor vasculature." (PMID 36831591, 2023). "Whereas, the mechanism of the combined anti-tumor effect of ORFV and PAK4 inhibitors is still unclear." (PMID 35401439, 2022). "In rhabdomyosarcoma, inhibition of PAK4 blocked the RAS-mediated signaling pathway and suppressed tumor growth in vivo." (PMID 36105226, 2022). "In this paper, we demonstrate that PAK4-NAMPT dual inhibition results in the suppression of cell growth and tumor growth reductions in DLBCL, FL, and MCL models." (PMID 35008323, 2021). "Another study illustrated that wild type and constitutively active PAK4 constructs alone were enough to lead to NIH3T3 cell transformation and tumor formation in athymic mice." (PMID 36594908, 2021). "Targeting cells which were dependent on GLUT3 by interfering with integrin and PAK4-YAP/TAZ signaling reduced GLUT3 expression and tumor cell viability, introducing a novel approach to treat this aggressive tumor type." (PMID 31690629, 2020). "We demonstrate that dual inhibition of PAK4 and NAMPT can block PNET proliferation in vitro and arrest tumor growth in mouse models." (PMID 31795447, 2019). "To study the anti-tumor efficacy of PD-1 blockade in the context of PAK4 deletion, we treated syngeneic C57BL/6 mice (n=7 each group) bearing either B16 PAK4 KO or B16 WT tumors with anti-PD-1." (PMID 30400822, 2018). "The relationships between DFS/OS and nine parameters including tumor size, lymph node status, histological grade, and AJCC stage, and expression of ER, PR, HER2, and PAK4 were assessed." (PMID 28407679, 2017). "PAK1 and PAK4 are activated differently, however little is known about the unique signalling pathways or the substrates of these two family members and how these differences may impact on the effect that these proteins have on the invasive potential of tumours." (PMID 27765920, 2016). "PAK4 expression in NSCLC tissues and adjacent non-tumor tissues were assessed by immunohistochemistry, real-time PCR, and western blotting." (PMID 25975262, 2015). "PAK4 was overexpressed at both protein and mRNA level in all 20 NSCLC tissues compared with the adjacent non-tumor tissues." (PMID 25975262, 2015). "Our previous report demonstrated that treatment with PF-3758309, a PAK4 inhibitor, produced maximal tumour growth inhibition when combined with gemcitabine in TKCC15-cell-derived tumours, which are comparatively more sensitive to gemcitabine (IC50 ≈ 5 nM) than PANC-1 cell lines." (PMID 41294859, 2025). "In human glioblastomas, PAK4 reduces the expression of intercellular adhesion molecule 1 (ICAM-1) and vascular cell adhesion molecule 1 (VCAM-1) via SLUG, thereby diminishing T cell adhesion to tumor endothelial cells." (PMID 40332759, 2025). "P21-activated kinase 1 (PAK1) and PAK4 play key roles in tumorigenesis, but their specific effects on tumour blood vessels and treatment response are not well understood." (PMID 41228228, 2025).